MYH6 (myosin heavy chain 6)
Diseases named in the same sentence as MYH6 in open-access papers (continued):
Sharing a sentence is not in itself a finding about the gene and the disease.
pulmonary hypertension (1 paper, 2022). Increased pressure within the pulmonary circulation due to lung or heart disorder. "Adult mutant (Parp1flox/flox;Tg+/Myh6-Cre, hereafter referred as conditional knockout [cKO]) and control (Parp1flox/flox designated as WT) mice were next exposed to Sugen/hypoxia to induce pulmonary hypertension." (PMID 35540097, 2022).
secundum-type atrial septal defects (1 paper, 2020). "Mutations in the head domain of MYH6 play a pivotal role in the progress of familial secundum-type atrial septal defects." (PMID 32631246, 2020).
Stroke (1 paper, 2021). Sudden impairment of blood flow to a part of the brain due to occlusion or rupture of an artery to the brain. "The MYH6 p.S180Y was located in the motor domain of myosin head, which associated with power stroke recovery and interaction with actin." (PMID 33949037, 2021). "The MYH6 p.I704N and p.D588A were located in the head domain and predicted to impair power stroke recovery and its interaction with actin, respectively." (PMID 33949037, 2021).
thrombosis (1 paper, 2022). "Some osmotic edema MYH6-Cre-BDNF–/– hearts also exhibited right atrial appendage thrombosis, left and right atrial thrombosis and/or left ventricular thrombosis." (PMID 36061561, 2022). "In addition to left atrial appendage thrombosis, some MYH6-Cre-BDNF–/– osmotic edema hearts also showed right atrial appendage thrombosis, left and right atrial thrombosis and left ventricular thrombosis." (PMID 36061561, 2022).
thymoma (1 paper, 2021). A neoplasm arising from the epithelial cells of the thymus. "Consistent with our analysis, MYH6 was differentially expressed in thymoma." (PMID 34104648, 2021). "By screening the DEGs that had a significant impact on the prognosis of thymoma, we identified LIPE, MYH6, ACTG2, KLF4, SULT4A1, and TF as key genes." (PMID 34104648, 2021). "This study identified key genes related to the prognosis of thymoma, including LIPE, MYH6, ACTG2, KLF4, SULT4A1, and TF." (PMID 34104648, 2021). "LIPE, MYH6, ACTG2, KLF4, SULT4A1, and TF were the key genes affecting the prognosis of thymoma." (PMID 34104648, 2021).
thyrotoxicosis (1 paper, 2014). A hypermetabolic syndrome caused by the elevation of thyroid hormone levels in the serum. "Their immunohistochemical study suggested an increase in the percentage of MYH6 during the course of thyrotoxicosis returning to normal levels following treatment." (PMID 24781449, 2014).
tricuspid atresia (1 paper, 2025). Tricuspid atresia is (TA) a rare congenital heart malformation characterized by the congenital agenesis of tricuspid valve leading to severe hypoplasia of right ventricle (functionally univentricular). "Patients in Group 1, the tricuspid atresia group, carried variants in the BMP2, MYH6, NFATC1, NOTCH1, and ZFPM2 genes, which have been reported to be associated with tricuspid atresia." (PMID 41153298, 2025).
virus infection (1 paper, 2021). "The expression of MYH6 mRNA levels is associated with virus infection." (PMID 34970603, 2021).
cardiac disease (16 papers, 2011 to 2026). "Many of the studies cited in this paper identified additional candidate variants that may be contributing to cardiac disease development, including some patients carrying compound heterozygous MYH6 variants." (PMID 35621855, 2022). "A representative example included the MYH6‐7 isoform switching, which was known to demonstrate opposite changes in cardiac diseases in humans versus rodents." (PMID 40459298, 2026). "The MYH6/MYH7 ratio is considered as a descriptive indicator of cardiac function, and the shift from MYH6 to MYH7 resulting in a decreased ratio indicated a maladaptive change in cardiac diseases." (PMID 35806390, 2022). "Reactivation of the fetal gene program is a classic indicator of cardiac disease remodeling; hence, expression levels of five commonly measured fetal genes (Acta1, Myh6, Myh7, Nppa and Nppb) were examined via real-time quantitative PCR (qPCR) from LV tissue." (PMID 31899774, 2020). "A Japanese study on 9 cases of SUDEP performed next-generation sequencing to examine 73 genes related to inherited heart disease: the Authors found KCNE1 as pathogenic variants (together with KCNE1) and also 3 other potentially pathogenic variants (MYH6, DSP, DSG2) according to in silico analysis." (PMID 41062843, 2026). "Thus, our data indicate that the predominant factor influencing MYH6 downregulation was the presence of cardiac disease itself." (PMID 41295372, 2025). "The upregulation of Myh7 and downregulation of Myh6 are common in human heart disease." (PMID 25890300, 2015). "We further highlight the necessity for ongoing research into the functional consequences of MYH6 and MYH7 deletions to improve our understanding of their role in the spectrum of cardiac diseases." (PMID 40004541, 2025). "Several SFRP4-targeted genes, such as MYH6, MYH7, TNNT2 and NKX2-5, contributed to different types of heart diseases." (PMID 32423033, 2020). "The genes MYH6, MYH7, and MYH12 might have a relationship with the occurrence and development of heart disease, although their regulatory mechanism in OS is unclear.ssGSEA showed that the immune cell infiltration score of high-risk OS patients was significantly lower." (PMID 37031292, 2023).
tumor (16 papers, 2012 to 2026). "Moreover, cardiac antigens, such as MYH6, are frequently expressed by the mutated tumor cells." (PMID 39023770, 2025). "Of these 7 survival-related genes, CSN3, KRT81, MUC7, and MYH6 has been elucidated to take part in tumor progression." (PMID 33530209, 2021). "Besides expression in tumor cells, other possible ways exist for the development and activation of MYH6-autoreactive T cells." (PMID 39023770, 2025). "Tumor microenvironment related genes ADGRG7, CSN3, CST8, KRT81, MUC7, MYH6, and SEZ6 are valuable predictors for HNSCC patient survival." (PMID 33530209, 2021). "MYH6 and MYH7, both on 14q11.2, were expectedly co-amplified and deleted in the same tumor samples with significant missense and truncation mutations distributed throughout both genes." (PMID 33217970, 2020).
cancer (15 papers, 2014 to 2024). A tumor composed of atypical neoplastic, often pleomorphic cells that invade other tissues. "The study reported that the potential muscle-specific genes expressed in cancer cells were TNNI1, TNNT1, DES, TRDN, MYH6, MYH11, and MYH13." (PMID 36378654, 2022). "However, some study using RNAi in vivo screen identified MYH6 frequently altered in HNSCC MOC lines and consider as novel putative cancer genes." (PMID 31692905, 2019). "While these observations may dismiss the prognosis utilities of MYLK2, as well as other recurrently perturbed actomyosin genes, e.g., MYH6 and MYH7, the specific functions of these genes still require a detailed functional interrogation in uterine as well as other cancer models." (PMID 33217970, 2020).
infection (9 papers, 2009 to 2025). The state of being infected such as from the introduction of a foreign agent such as serum, vaccine, antigenic substance or organism. "The authors found that infection in Myh6-Cre hACE2 KI mice was rapidly cleared from the heart (by 7 days post-infection) and led to left ventricular systolic dysfunction, which was driven by CCR2-dependent infiltration of monocytes into the heart." (PMID 39861887, 2025). "In a whole well of a 12-well plate, less than 10 mCherry+ cells (<0.1%) were observed after 2 weeks of GMT infection with Myh6-reporter transgenic MICFs." (PMID 33718351, 2021). "In our experimental conditions, the infection of RNVC with adMek1ca provokes a 60% decrease in Myh6, Mef2c, and Gata4 mRNA expression and a 40% decrease in Srf mRNA expression." (PMID 30206251, 2018).
myopathy (7 papers, 2013 to 2024). A disease of the muscle in which the muscle fibers do not function properly. "The levels of MYH6 and MYH7 expression have also been considered as markers for the severity of myopathy." (PMID 25750702, 2015).
cardiovascular disease (3 papers, 2020 to 2024). "A reduction of the Myh6/Myh7 expression ratio is a well-established molecular marker of maladaptive cardiac remodeling and a target of therapeutic intervention to contrast cardiovascular disease evolution." (PMID 32987653, 2020).
metabolic disorders (1 paper, 2022). "Indeed, IPA identified pathways and gene interaction networks involved in increased heart apoptosis, activation of cardiac inflammation and ROS, and increased body weight and metabolic disorders in MYH6-Cre-BDNF–/– hearts." (PMID 36061561, 2022).
MYH6 also shares sentences with these, for which no sentence is quoted: autoimmune myocarditis (11 papers); Cachexia (5); cardiac arrhythmias (4); muscle atrophy (4); Atrophy (3); congenital myopathy (3); coronary artery disease (3); familial hypertrophic cardiomyopathy (3); muscular dystrophy (3); atrial septal defect 3 (2); Autoimmunity (2); distal myopathy (2); Duchenne muscular dystrophy (2); emphysema (2); Freeman-Sheldon syndrome (2); hypertrophy (2); multiple pterygium syndrome (2); muscle disorders (2); muscular atrophy (2); rhabdomyosarcoma (2); Spondylocarpotarsal synostosis (2); ventricular tachycardia (2); acute myocardial infarction (1); acute myocarditis (1); albinism (1); Alzheimer disease (1); Anxiety (1); atrioventricular septal defect (1); Becker muscular dystrophy (1); Brugada syndrome (1).
A further 46 diseases each share a sentence with MYH6 in 1 paper.